SVBP (small vasohibin binding protein)
Description:
Enhances the tyrosine carboxypeptidase activity of VASH1 and VASH2, thereby promoting the removal of the C-terminal tyrosine residue of alpha-tubulin. This activity is critical for spindle function and accurate chromosome segregation during mitosis since microtubule detyrosination regulates mitotic spindle length and postioning. Also required to enhance the solubility and secretion of VASH1 and VASH2. Plays a role in axon and excitatory synapse formation.
Synonyms: CCDC23; MGC45441; NEDAHM; SPG94
Tractability: Small molecule: a structure with a bound ligand is known. Antibody: UniProt places it where antibodies can reach, with medium confidence; its Gene Ontology location is reachable by antibodies, with medium confidence. PROTAC: its protein half-life has been measured.
Gene: Protein-coding gene on chromosome 1 (42,807,040 to 42,817,397, reverse strand). Ensembl gene ENSG00000177868.
Subcellular location: Cytoplasm; Secreted; Cytoplasm, cytoskeleton
Subcellular location (Human Protein Atlas): Cytosol; Nuclear bodies; Nucleoplasm; Predicted to be secreted
Pathways (Reactome):
Metabolism of proteins: Carboxyterminal post-translational modifications of tubulin
Gene Ontology:
Molecular function: microtubule binding; peptidase activator activity; protein binding
Biological process: axon development; negative regulation of endothelial cell migration; negative regulation of protein ubiquitination; protein secretion; proteolysis; regulation of metallopeptidase activity
Cellular component: apical part of cell; cytoplasm; extracellular region; cytoskeleton
Genetic constraint (gnomAD): Loss-of-function variants: 4 observed, 3.69 expected, observed/expected ratio (o/e) 1.08, 90% interval 0.51 to 1.87. That is too few expected variants to judge how well the gene tolerates losing a copy. Missense variants: 22 observed, 29.79 expected, observed/expected ratio (o/e) 0.74, 90% interval 0.53 to 1.05. Synonymous variants: 12 observed, 10.57 expected, observed/expected ratio (o/e) 1.14, 90% interval 0.72 to 1.76.
Homologues: Orthologues: chimpanzee SVBP (100% identical), macaque SVBP (98% identical), dog SVBP (95% identical), guinea pig SVBP (95% identical), mouse Svbp (94% identical), rat Svbp (94% identical), tropical clawed frog svbp (70% identical), zebrafish svbp (67% identical).
Diseases named in the same sentence as SVBP in open-access papers:
SVBP is named in the same sentence as 12 diseases in open-access papers, as found by Europe PMC text mining. Sharing a sentence is not in itself a finding about the gene and the disease. The quoted sentences say what the papers report.
Intellectual disability (3 papers, 2020 to 2025). "Patients with loss‐of‐function mutations in SVBP (small vasohibin‐binding protein) were reported to exhibit symptoms such as ataxia, intellectual disability, microcephaly, and muscular hypotonia." (PMID 39412222, 2025). "Loss-of-function mutations of SVBP in humans have been associated with brain abnormalities, including microcephaly, ataxia, and intellectual disability." (PMID 32773040, 2020). "Biallelic loss-of-function mutations of SVBP in humans have been linked to brain development defects and intellectual disability." (PMID 32773040, 2020). "Taken together, our findings underscore the critical role of SVBP in the development and maintenance of the central nervous system, providing novel insights associating cytokinesis failure with cortical motor neuron disease and intellectual disability." (PMID 39412222, 2025). "SVBP deficiency in humans can lead to pathogenic neurodevelopment, and rare SVBP biallelic variants were found to induce defects in the brain associated with mental retardation." (PMID 40497943, 2025). "In this study, we have identified a novel biallelic missense variant in SVBP among six individuals exhibiting spastic paraparesis accompanied by sensorimotor axonal neuropathy, verbal apraxia, epilepsy, and intellectual disability, thereby expanding the previously reported phenotype." (PMID 39412222, 2025). "These affected individuals present with a complex hereditary spastic paraplegia (HSP), peripheral neuropathy, verbal apraxia, and intellectual disability, exhibiting a milder phenotype compared to patients with nonsense SVBP mutations described previously." (PMID 39412222, 2025).
Brain atrophy (1 paper, 2025). Partial or complete wasting (loss) of brain tissue that was once present. "Furthermore, cultured neurons lacking SVBP displayed a clear delay in axon differentiation and severe morphological defects, suggesting that the brain atrophy observed in SVBP knockout mice likely originates from abnormal differentiation and maturation of deficient neurons." (PMID 39412222, 2025).
cancer (2 papers, 2020 to 2024). A tumor composed of atypical neoplastic, often pleomorphic cells that invade other tissues. "The recent discovery of the vasohibin (VASH)/small vasohibin-binding protein (SVBP) complex, reported as a detyrosinating enzyme, tubulin carboxypeptidase (TCP), provides new links between this tubulin modification and already known associations between vasohibin dysfunction and cancer." (PMID 32823874, 2020).
neurological disorders (1 paper, 2025). "In summary, we describe a novel SVBP variant resulting in neurodevelopmental delay and complex HSP in several patients, and our molecular findings underscore centrosome defects and replicative senescence as major paradigms in the pathogenesis of neurological disorders." (PMID 39412222, 2025).
SVBP also shares sentences with these, for which no sentence is quoted: breast carcinoma (1 paper); dystrophinopathies (1); glioma (1); hereditary spastic paraplegia (1); peripheral neuropathy (1); renal disorders (1); Spastic paraplegia (1); tumor (1).